IFNG (interferon gamma)
Diseases named in the same sentence as IFNG in open-access papers (continued):
Sharing a sentence is not in itself a finding about the gene and the disease.
lichen planus (12 papers, 2012 to 2025). A chronic, recurrent, pruritic inflammatory disorder of unknown etiology that affects the skin and mucus membranes. "In lichen planus, this expression is triggered by the induction of interferon gamma (IFN-γ)." (PMID 39194725, 2024).
migraine (12 papers, 2019 to 2025). "Nasal administration of IFNγ-DC-EVs also inhibits spreading depression, the likely cause of migraine aura and a well-established experimental model of migraine." (PMID 34388189, 2021). "Environmental enrichment-mediated changes in dendritic cell exosomes, such as IFNγ-DC-Exos, have shown promise in reducing susceptibility to spreading depression, a potential mechanism underlying migraine, suggesting a therapeutic potential for migraine treatment." (PMID 39407099, 2024). "In our ex vivo preparation, pro-inflammatory cytokines (i.e., IL-6, IL-10, MCP-1, TNFα, IL-12p70, and IFNγ) are released and detectable already at basal conditions, confirming the local source of inflammatory stimuli that can trigger migraine." (PMID 35614095, 2022). "Here we review the benefits of environmental enrichment for migraine treatment, and discuss the potential of using extracellular vesicles derived from interferon gamma-stimulated dendritic cells as an effective mimetic." (PMID 34337600, 2021). "We found that administration of IFNγ-DC-Exos reduced susceptibility to spreading depression in vivo and in vitro, suggesting that IFNγ-DC-Exos may be a potential therapeutic for migraine." (PMID 31551696, 2019). "This led us to explore the ability of IFNγ-DC-Exos to mitigate SD as a model of migraine with aura." (PMID 31551696, 2019). "Taken together, this suggests IFNγ-DC-EVs may be a potent EE-mimetic for use in migraine treatment." (PMID 34337600, 2021).
myeloid leukemia (12 papers, 2012 to 2026). A clonal proliferation of myeloid cells and their precursors in the bone marrow, peripheral blood, and spleen. "ENCFF020ODE is the interferon regulatory factor 1 (IRF1) ChIP-seq data from human K562 cells, a human immortalized myelogenous leukemia cell line, treated with Interferon gamma (IFN-γ)." (PMID 38032891, 2023).
neuropathy (12 papers, 2013 to 2024). A disorder affecting the nervous system that manifests with pain, tingling, numbness, and/or muscle weakness. "While some studies provide evidence for the association between this IFNγ polymorphism and diabetic retinopathy (the Indian ethnic group) and with neuropathy (the South Indian patients), others (Brazilian individuals) do not confirm its existence." (PMID 30862026, 2019). "Previous studies also demonstrate that proinflammatory cytokine IFNγ plays an obligatory role in the development of neuropathy as NOD B7-2−/− and NOD.AireGW/+ mice (a dominant G228W mutation of Aire gene) deficient in IFNγ are completely protected from disease." (PMID 29615658, 2018).
plague (12 papers, 2007 to 2024). Plague is a severe bacterial infection caused by the gram-negative bacterium Yersinia pestis. "An IFNγ-dependent type 1 immune response is essential for vaccine-induced protection against plague." (PMID 26473734, 2015).
prostate tumor (12 papers, 2010 to 2025). "In conclusion, our analysis supports a model in which IFNG-expressing T cells within both primary and metastatic prostate tumors systemically upregulate IFNG signaling in bone marrow myeloid cells of the premetastatic niche." (PMID 40875516, 2025). "Concomitantly, prostate tumor cells directly inhibit secretion of IFNγ as a effector function in iNKT cells." (PMID 20593019, 2010). "The inverse correlation between level of IFNγ and both treatment response, outcomes, and prostate tumor differentiation in mCRPC patients in this study may suggest an adverse effect of NK cells at that stage." (PMID 37816781, 2023). "Thus, it is conceivable that prostate tumor cells, in addition to CD1d-mediated signals activating iNKT cells deliver additional signals that block the translation or export of IFNγ in iNKT." (PMID 20593019, 2010). "In contrast, a recent study found that prostate tumors with PTEN loss exhibited strong activation of both innate and adaptive immune systems, with increased interferon-gamma response genes and CD8+ lymphocytes, suggesting they may respond better to immunotherapies." (PMID 40650023, 2025). "When splenocytes from these mice were cocultured with either parental B16 or TC2 prostate tumor cells expressing either CSDE1 or CSDE1* epitopes, only mice vaccinated with B16-CSDE1* and treated with ICB showed an IFNγ recall response against parental B16 cells (p < 0.01 one-way ANOVA)." (PMID 32034147, 2020). "Indeed, treatment with IFNγ alone or combined IFNγ and TNFα, but not TNFα alone, sensitized PTPN2- or STUB1-null prostate tumour cells to growth inhibition via measuring the ATP level produced by viable cells." (PMID 35982220, 2022).
spondyloarthritis (12 papers, 2009 to 2025). "Given that γδT cells can produce the pro-inflammatory cytokines TNFα and IFNγ, which are involved in the pathogenesis of RA and spondyloarthritis, it is possible that pregnancy induces some dampening of the TNFα- or IFNγ-producing Vδ1 and Vδ2 cells." (PMID 26795030, 2016). "Patients fulfilling either the modified New York criteria for ankylosing spondylitis or Assessment in SpondyloArthritis international Society criteria and who were refractory to oral treatment were screened with Mantoux (≥10mm) and interferon gamma release assay (QuantiFERON) to detected LTBI." (PMID 31057626, 2019).
thymoma (12 papers, 2014 to 2025). A neoplasm arising from the epithelial cells of the thymus. "In mice bearing EL4 thymoma, 5-FU selectively deplete MDSCs thus restoring IFNγ production by CD8+ T cells." (PMID 31530882, 2019).
atopic asthma (11 papers, 2009 to 2022). An asthma that is characterized by symptoms that are triggered by an allergic reaction caused by inhaled allergens such as dust mite allergen, pet dander, pollen and mold. "It was found that the polymorphisms in the intronic region of IFNγ gene may be critical for IFNγ gene regulation and atopic asthma." (PMID 19419542, 2009). "Another study in children with atopic asthma showed an increase in the percentage of CD4 and CD8 cells producing IL-4 and a decrease in CD4 cells producing IFNγ in comparison with healthy controls, while the percentage of cells producing TNF remained unchanged." (PMID 27799958, 2016).
atrial fibrillation (11 papers, 2018 to 2025). A disorder characterized by an electrocardiographic finding of a supraventricular arrhythmia characterized by the replacement of consistent P waves by rapid oscillations or fibrillatory waves that vary in size, shape and timing and are accompanied by an irregular ventricular response. "Increased levels of IFNγ have been observed in ischemic heart disease, dilated cardiomyopathy, and have been identified as a reliable predictor of strokes in patients with atrial fibrillation." (PMID 40104808, 2025).
autoimmune encephalitis (11 papers, 2009 to 2025). Inflammation of the brain secondary to an immune response triggered by the body itself. "Although this represents a modest proportion of Eomes + Tbet + cells, this is consistent with mouse data from experimental autoimmune encephalitis showing the capacity of Eomes + IFNγ+CD4 T cells to acquire cytotoxic attributes." (PMID 36726536, 2023). "For example, the consistent differential in time between the expression of interferon gamma and IL-17 during active experimental autoimmune encephalitis in DA rats suggests different roles for these cytokines in the pathogenesis of the disease." (PMID 20038977, 2009). "In line with our hypothesis, it was recently shown that the blockade of IFNγ signaling in astrocytes alone leads to a reduced inflammatory reaction, whereas the blockage of IFNγ signaling in microglia supports inflammation in an autoimmune encephalitis model." (PMID 31186414, 2019).
bronchiectasis (11 papers, 2014 to 2025). Segmental, irreversible dilation of the bronchial tree resulting in the accumulation of secretions which leads to obstruction. "In contrast to our observations, NTHi challenged PBMC from adults with bronchiectasis produced less IFNγ but equal proportions of CD107a+ NK cells (and CD107a+ CD8+ T cells) in comparison with PBMC from healthy adult controls." (PMID 29621281, 2018). "Notably, we did not identify a difference in the T-cell memory phenotype between CPA patients and bronchiectasis controls, supporting the idea that IFNγ deficiency is not a consequence of T-cell dysfunction but rather caused by the failure of cDCs to drive effective Th1 activation." (PMID 40503945, 2025). "Studies in children with chronic suppurative lung disease (CSLD) and adults with bronchiectasis have revealed impaired CD8+ T cell, Natural Killer (NK) cell and interferon-γ (IFNγ) production in response to NTHi challenge." (PMID 29621281, 2018). "Although a specific role for IFNγ in clearing NTHi infection has not been identified, PBMCs from children with chronic suppurative lung disease and adults with bronchiectasis have been shown to have impaired IFNγ production in response to NTHi challenge." (PMID 27242968, 2016).
contact dermatitis (11 papers, 2008 to 2025). An inflammatory skin condition caused by direct contact between the skin and either an irritating substance or an allergen. "RT-PCR analyses also revealed mRNA upregulation of pro-inflammatory cytokines (IL-1β and IL-6) and some Th1 or Th2 cytokines (IFNγ, IL-4, and IL-10), but not that of IL-2, TGFβ, and IL-17, at the delayed phase of oxazolone-induced contact dermatitis, similar within the three genotypes." (PMID 36768979, 2023).
delirium (11 papers, 2014 to 2025). A disorder characterized by confusion; inattentiveness; disorientation; illusions; hallucinations; agitation; and in some instances autonomic nervous system overactivity. "Among the pro-inflammatory cytokines, TNFα is upstream of 17 of the 32 CSF delirium-associated proteins, IFNγ has a potential connection to 15/32 CSF proteins, IL-6 is upstream of 10/32 proteins, and IL-10 is upstream of 8/32 proteins." (PMID 37759795, 2023). "In addition, increased serum interferon gamma (IFN-γ) and decreases in insulin-like growth factor (IGF)-1 and IL-1 have been associated with delirium in elderly patients receiving medical treatment." (PMID 38076249, 2023). "Increased serum interferon gamma (IFN-γ), and decreases in the anti-inflammatory insulin-like growth factor 1 (IGF-1) and IL-1ra have been demonstrated in elderly medical patients with delirium." (PMID 25124807, 2014).
gingivitis (11 papers, 2015 to 2026). A disorder involving inflammation of the gums; may affect surrounding and supporting structures of the teeth. "The methylation levels of all sites analyzed within the IFNG promoter region were significantly lower in the CP samples compared to gingivitis and healthy control samples." (PMID 32867386, 2020). "Zhang (2010) examined IFNG as a candidate gene in experimental gingivitis samples compared to CP and healthy controls samples; the group reported a statistically significant hypomethylation in experimental gingivitis and CP samples, compared to control samples." (PMID 32867386, 2020). "Unlike in GCF, salivary TNFα and IFNγ were elevated in T1DM across all periodontal statuses, with significant increases in gingivitis (TNF-α, p < 0.0001) and healthy (IFNγ, p < 0.05) groups." (PMID 41280935, 2025).
hemorrhage (11 papers, 2013 to 2026). Loss of blood from the vascular compartment to the exterior or into nonvascular body space as a result of rupture or severance of the blood vessels. "The first heatmap analysis clearly demonstrates a significant reduction in larvae recovery, IFNγ, TNF, and hemorrhage in the reinfected (RE) groups compared to single-infected (SI) counterparts." (PMID 39621794, 2024).
intestinal inflammation (11 papers, 2010 to 2023). "In particular the IL-23 suppressing ability of IFNγ supports the finding, where hall-mark Th1-promoting cytokines have the ability to suppress the Th17 promoting phenotype, a potential cross-talk discussed extensively for inflammatory diseases particular for intestinal inflammation." (PMID 20663192, 2010).
keloid (11 papers, 2015 to 2025). An irregularly shaped, elevated mark on the skin caused by deposits of excessive amounts of collagen during wound healing. "Meanwhile, Si-IFNγ combined with si-SPOCD1 can further reduce the impact of si-IFNγ on keloid tissue, thereby reducing the cell migration rate." (PMID 39820341, 2025). "In these simulations, we have also confirmed the inhibitory impact of si-SPOCD1 on keloid growth, diminishing the propensity for KD to form new blood vessels, and the modulation of IFNγ on SPOCD1." (PMID 39820341, 2025). "To delve deeper into the role of IFNγ in keloid development, we supplemented KFs supernatant with erastin, a ferroptosis inducer, along with IFNγ for a 24-hour period." (PMID 39820341, 2025). "This further motivates us to study the expression of IFNγ in keloid." (PMID 39820341, 2025). "Thus, IFNγ signaling paired with SPOCD1 is a natural keloid ferroptosis promoting mechanism and a mode of action of CTLs." (PMID 39820341, 2025). "To reveal the relationship between IFNγ and DNMT3A, we hypothesized the DNMT family induced hypermethylation of IFNγ promoter in keloid so as to decrease its expression." (PMID 39820341, 2025). "The expression of IFNγ in KFs as well as in keloid is decreasing." (PMID 39820341, 2025). "What’s more, IFNγ has a synergistic relationship with DNMT3A in keloids." (PMID 39820341, 2025). "All these results suggest that IFNγ may regulate SPOCD1expression in keloid by DNA methylation indirectly, which in turn affects ferroptosis process regulated through IFNγ." (PMID 39820341, 2025). "We also found that the proportion of CD8 Teff (IFNG+) was consistently increased in keloids and normal scars compared to healthy skin, suggesting that the cells may play a role in scar formation." (PMID 39872534, 2024). "Decreased levels of IFNγ have been observed in the blood of keloid patients." (PMID 26540410, 2015). "Our results associate keloid tissues with an inflammatory milieu representing multiple T-helper pathways, including the Th2 (e.g. IL-4R, CCL11, TSLP, TNFSF4/OX40L, TNFRSF4/OX40), Th1 (e.g. IFNγ, CXCL10/11), Th17/Th22 (e.g. PI3, CCL20, S100As) axes, as well as the JAK/STAT signaling molecule JAK3." (PMID 33329590, 2020). "Hence, we hypothesized that the expression of IFNγ in keloid was also related with DNA methylation." (PMID 39820341, 2025). "The regulatory relationship between IFNγ and SPOCD1 may emerge as a novel target for treating keloid and preventing their recurrence." (PMID 39820341, 2025). "Decreased levels of the antifibrotic Th1 cytokines IFNγ and IFNα have been reported for African Americans with keloids compared to those without keloids." (PMID 26540410, 2015). "Hence, the increase rate of CD31+/ CD34+ implies that si-SPOCD1 and si- IFNγ + SPOCD1 can diminish the stemness of vascular endothelial cells, curtail the neovascularization within the vascular endothelium of keloid, thereby inhibiting the growth of keloid." (PMID 39820341, 2025).
medulloblastoma (11 papers, 2011 to 2024). A malignant, invasive embryonal neoplasm arising from the cerebellum. "A recent study reported that IFNγ-associated PD-L1 upregulation in medulloblastoma is mediated by CDK5, the depletion of which downregulates PD-L1 in malignant cells." (PMID 34479614, 2021). "In another study of IFNγ transgenic mice with targeted astrocyte overexpression, IFNγ induced tumorigenesis including a high incidence of medulloblastoma in the cerebellum, a condition thought to involve immature cerebellar granule neuron precursors." (PMID 37950146, 2024). "IFNγ-mediated caspase 8 upregulation was also shown to enhance sensitivity of medulloblastoma cells to standard chemotherapeutic agents including cisplatin, doxorubicin, and etoposide, as well as to ionising radiation." (PMID 35568716, 2022). "Furthermore, interferon-γ (IFNγ) treatment of caspase 8 deficient cells restored caspase 8 expression and TRAIL sensitivity in TRAIL-resistant medulloblastoma and neuroblastoma cell lines." (PMID 35568716, 2022). "Interestingly, ectopic expression of IFNγ during early stages of CNS development induces medulloblastomas via SHH overexpression pointing towards a general dysregulating effect of IFNγ on NSPCs during development or disease." (PMID 21371330, 2011). "In pediatric medulloblastoma, it has been revealed that B7-H3 CAR T cells, by producing IFNg, TNFa, and IL-2, can have antitumor effects in xenograft models." (PMID 33673696, 2021). "Interestingly, in mice a link between IFNγ and SHH signaling was observed as an ectopic expression of IFNγ was shown to induce medulloblastoma formation via SHH overexpression." (PMID 23162429, 2012).
mucormycosis (11 papers, 2015 to 2025). "A combination of immunotherapy and IFNγ was proven to be an effective treatment for intractable invasive mucormycosis." (PMID 35628701, 2022). "Just like in the pulmonary infection, in disseminated mucormycosis, IL-17 signaling and the Th1- response, through IFNγ signaling, are crucial for fungal clearance and thus control of the infection." (PMID 35628701, 2022).
nematode infection (11 papers, 2011 to 2025). "In fact, IFNγ production and T. muris worm burdens in wild-type mice kept outdoors for the short term were nearly as high as those of STAT6-/- mice that are genetically susceptible to nematode infection." (PMID 29518091, 2018).
nonalcoholic steatohepatitis (11 papers, 2013 to 2025). "To date, a human study in obese children first associated increased Th1 cells and their release of IFNγ with nonalcoholic steatohepatitis and insulin resistance." (PMID 28466852, 2017). "In HFD-fed mice, we found nonalcoholic steatohepatitis, increased gene expression of TNFα, IFNγ, MCP-1, caspase-3, TGFβ1 and collagen α1(I), and increased levels of 3-tyrosine nitrated proteins." (PMID 25261569, 2014).
osteopetrosis (11 papers, 2013 to 2023). Osteopetrosis, also known as marble bone disease, is a descriptive term that refers to a group of rare, heritable disorders of the skeleton characterized by increased bone density on radiographs. "The use of IFNγ in humans has been suggested to employ IFNγ for the treatment of osteopetrosis, in which condition IFNγ is able to restore bone resorption." (PMID 23935650, 2013). "In humans the weight of evidence is in favor of a net pro-osteoclastogenic activity as clinical studies have employed IFNγ to treat excessive bone formation by stimulating bone resorption in osteopetrosis." (PMID 24278766, 2013). "The data suggesting antiosteoporotic actions of IFNγ conflict, however, with a number of clinical studies that have used IFNγ administration to treat excessive bone formation by upregulating bone resorption in conditions of osteopetrosis." (PMID 24278766, 2013). "As for other general form of osteopetrosis, a clinical trial on interferon gamma −1b for intermediate osteopetrosis had just completed its phase 2 in April 2019, and results are pending (ACTIMMUNE in Intermediate Osteopetrosis; ClinicalTrials.gov Identifier: NCT02666768)." (PMID 34056870, 2021).
renal failure (11 papers, 2012 to 2024). "High IFNγ at admission was the only predictor of developing kidney failure." (PMID 34608231, 2021).